TXLNA (taxilin alpha)
Description:
May be involved in intracellular vesicle traffic and potentially in calcium-dependent exocytosis in neuroendocrine cells.
Synonyms: TXLN; DKFZp451J0118; IL-14; IL14
Tractability: PROTAC: ubiquitination databases record sites on it; its protein half-life has been measured.
Gene: Protein-coding gene on chromosome 1 (32,178,097 to 32,198,299, forward strand). Ensembl gene ENSG00000084652.
Subcellular location (Human Protein Atlas): Cytosol; Centrosome; Nucleoplasm
Pathways (Reactome):
Immune System: Other interleukin signaling
Gene Ontology:
Molecular function: protein binding
Cellular component: cytoplasm; membrane; cytosol; extracellular region
Genetic constraint (gnomAD): Loss-of-function variants: 10 observed, 56.46 expected, observed/expected ratio (o/e) 0.18, 90% interval 0.11 to 0.3. The upper end of that interval is the gene's LOEUF score, 0.3, which puts it in group 1 of 6, group 1 being the genes least tolerant of losing a copy. Missense variants: 563 observed, 693.61 expected, observed/expected ratio (o/e) 0.81, 90% interval 0.76 to 0.87. Synonymous variants: 256 observed, 268.53 expected, observed/expected ratio (o/e) 0.95, 90% interval 0.86 to 1.06.
Homologues: Orthologues: chimpanzee TXLNA (99% identical), macaque TXLNA (99% identical), dog TXLNA (94% identical), rabbit TXLNA (93% identical), guinea pig TXLNA (92% identical), pig TXLNA (92% identical), mouse Txlna (90% identical), rat Txlna (90% identical), zebrafish txlna (61% identical), tropical clawed frog txlna (53% identical). Paralogues in human: TXLNG (49% identical), TXLNB (49% identical).
Diseases named in the same sentence as TXLNA in open-access papers:
TXLNA is named in the same sentence as 32 diseases in open-access papers, as found by Europe PMC text mining. Sharing a sentence is not in itself a finding about the gene and the disease. The quoted sentences say what the papers report.
pancreatic cancer (5 papers, 2020 to 2024). "Alpha‐taxilin (TXLNA) has been reported in renal cell cancer, hepatocellular cancer, and pancreatic cancer." (PMID 38738791, 2024). "In the research on pancreatic cancer, it was concluded that the high expression of TXLNA suggests a favorable prognosis for patients." (PMID 37752559, 2023). "TXLNA, for example, is a cancer suppressor gene in pancreatic cancer, yet it is a promoter of tumors in hepatocellular carcinoma and renal cell carcinoma, thus inducing their emergence and development." (PMID 37752559, 2023). "More than that, a few Studies have established TXLNA’s existence and manifestation in hepatocellular carcinoma, renal cell carcinoma, and pancreatic tumor cells." (PMID 37752559, 2023). "The relationship between TXLNA and pancreatic cancer prognosis remains to be determined." (PMID 32185195, 2020). "Nevertheless, the role of TXLNA on pancreatic cancer remains unknown." (PMID 32185195, 2020).
glioma (4 papers, 2023 to 2024). A benign or malignant brain and spinal cord tumor that arises from glial cells (astrocytes, oligodendrocytes, ependymal cells). "Conversely, TXLNA, also referred to as IL-14, is identified as a high-molecular-weight B cell growth factor, and its ectopic expression has often been linked to dismal prognostic outcomes in glioma." (PMID 38933262, 2024). "The occurrence and development of tumors, though not due to a single cause, is still influenced by many factors; thus, it is uncertain if TXLNA can be a distinct risk factor for glioma patients." (PMID 37752559, 2023). "A poor prognosis in glioma patients is associated with a high TXLNA expression (p < 0.05)." (PMID 37752559, 2023). "ATOR blocked the viability, proliferation, migration, and invasion of U87 cells through the miR-125a-5p/TXLNA axis, and suppressed glycolysis and immune escape of glioma cells." (PMID 39726023, 2024). "Rescue experimental results exhibited that suppressing miR-125a-5p impaired the inhibitory effects of ATOR on glioma cells, while overexpressing TXLNA enhanced the effects of suppressing miR-125a-5p on glioma cells." (PMID 39726023, 2024). "The aim of this study was to investigate the effects of ATOR on glioma cell biological functions, glycolysis levels and immune escape via the miR-125a-5p/TXLNA axis." (PMID 39726023, 2024). "ATOR inhibits tumor glycolysis and immune escape through miR-125a-5p-mediated regulation of TXLNA, thereby contributing to the alleviation of glioma progression." (PMID 39726023, 2024). "This study explored the molecular and clinical characteristics of TXLNA in gliomas through bioinformatics analysis, and reached corresponding conclusions." (PMID 37752559, 2023). "According to the expression difference of TXLNA, We split the samples into two distinct groups, one with high TXLNA expression and the other with low TXLNA expression, to explore the effects of TXLNA on glioma patients." (PMID 37752559, 2023). "Pearson’s correlation test was employed to further elucidate TXLNA’s part in the pathogenesis of gliomas, and TXLNA related genes were pinpointed." (PMID 37752559, 2023). "The Kaplan-Meier survival curve was employed to preliminarily evaluate the survival curves of the high and low expression groups, this was done for investigate the correlation between TXLNA expression level and the survival and prognosis of glioma." (PMID 37752559, 2023). "By identifying TXLNA enrichment pathways, we can indirectly understand what pathways TXLNA regulates to affect the occurrence of glioma." (PMID 37752559, 2023). "TXLNA’s involvement in the glioma regulatory network is demonstrated through its interaction with cancer genes and cancer suppressor genes." (PMID 37752559, 2023). "The expression of TXLNA in glioblastoma and low-grade glioma was observably higher than that of normal brain tissue (P < 0.05)." (PMID 37752559, 2023). "TXLNA expression in glioma tissues is far greater than in normal tissues, and its upsurge is associated with a reduced likelihood of survival and a dismal outlook." (PMID 37752559, 2023). "TXLNA in gliomas was elevated, but TXLNA expression decreased with increasing ATOR concentration." (PMID 39726023, 2024). "Until now, there has been a dearth of systematic and thorough research into the bioinformatics analysis of TXLNA about expression difference in brain gliomas, their clinical importance, and their mechanism of action, despite PCR analysis of TXLNA genes in glioma patients having been conducted." (PMID 37752559, 2023). "Gene pool enrichment analysis(GSEA)was used to investigate the related function of TXLNA in glioma." (PMID 37752559, 2023). "However, there is still a lack of laboratory data to support the relationship between some pathways and TXLNA expression in glioma cells or tumor cells." (PMID 37752559, 2023). "Nevertheless, the role of TXLNA in glioma is still a mystery." (PMID 37752559, 2023).
glioma (continued). "Therefore, the specific function of TXLNA in glioma, whether it accelerates the pathological process of glioma or regards as a target for clinical therapy, still requires a large amount of data analysis." (PMID 37752559, 2023). "Therefore, these pathways can be considered as potential pathways for TXLNA regulation in glioma." (PMID 37752559, 2023). "ATOR blocks glioma progression by modulating the miR-125a-5p/TXLNA axis, further demonstrating that ATOR provides an effective therapeutic target for the treatment of glioma." (PMID 39726023, 2024). "A marked divergence in TXLNA expression between glioma and normal brain tissue was uncovered by our findings, and a negative relationship between TXLNA expression and OS in glioma patients was also observed." (PMID 37752559, 2023). "Among them, IFNGR2, TXLNA, PSMC2, and TMSB15A have not been reported to be associated with gliomas." (PMID 37867596, 2023).
pancreatic adenocarcinoma (2 papers, 2020 to 2021). "miR-1271 targeted TXLNA, and high TXLNA expression could be a favorable biomarker and therapeutic target for pancreatic adenocarcinoma patients." (PMID 34763659, 2021). "However, the accurate relation between TXLNA and tumorigenesis and progression of pancreatic adenocarcinoma (PAAD) is still unclear." (PMID 32185195, 2020).
hepatitis B (1 paper, 2024). "Specifically, TXLNA was linked to hepatitis B, SVMRS to hepatitis C, and RAET1E to non-alcoholic fatty liver disease." (PMID 38933262, 2024).
tumor (7 papers, 2019 to 2025). "A Cox regression model was used to evaluate the relationship between TXLNA expression, clinical characteristics and prognosis, from which we found that tumor recurrence, age, and IDH mutation were closely related to the survival rate of GBM patients." (PMID 37752559, 2023). "Taxilin alpha (TXLNA), also known as interleukin 14 (IL-14), highly expressed in various tumor cells, is a binding partner of the syntaxin family that can coordinate intracellular vesicle trafficking." (PMID 40034328, 2025). "This study confirmed that inhibition of tumor glycolysis and immune escape by the miR-125a-5p/TXLNA axis is critical for suppressing tumor cell proliferation and progression." (PMID 39726023, 2024). "ATOR therapy was further explored, and the molecular function of miR-125a-5p/TXLNA in tumor progression was greatly expanded." (PMID 39726023, 2024). "A correlation between TXLNA expression and tumor grade was demonstrated, with the expression of TXLNA gradually augmenting with the augmentation of tumor grade (p < 0.001)." (PMID 37752559, 2023). "Recent studies demonstrate that the TXLNA protein had a high expression in various tumor cells and its expression indicates a close relationship with histological grade and proliferative activity in hepatocellular carcinoma, as well as the metastatic and invasive potential of renal cell carcinoma." (PMID 32185195, 2020). "TXLNA (taxilin alpha), a binding partner of the syntaxin family, was identified as a key factor in the coordination of intracellular vesicle trafficking and highly expressed in various tumor cells." (PMID 32185195, 2020). "This function of TXLNA suggests that it may participate in the gene expression of tumor cells." (PMID 37752559, 2023).
cancer (4 papers, 2016 to 2023). A tumor composed of atypical neoplastic, often pleomorphic cells that invade other tissues. "The prognosis of GBM patients is strongly linked to the high expression of TXLNA, which may be a viable therapeutic target for curbing cancer progression and creating new immunotherapies for GBM." (PMID 37752559, 2023).
genetic diseases (1 paper, 2024). "We identified four high-impact variants in four candidate novel genes (ZBTB38, AQR, APBA1, and TXLNA) not implicated before in NDD or genetic diseases in four probands/families." (PMID 38300321, 2024).
respiratory diseases (1 paper, 2020). "Recent studies indicate that TXLNA was involved in inflammation, endocrine, and respiratory diseases." (PMID 32185195, 2020).
TXLNA also shares sentences with these, for which no sentence is quoted: hepatocellular carcinoma (2 papers); renal cell carcinoma (2); allergic asthma (1); asthma (1); atrophic gastritis (1); B-cell non-Hodgkin lymphoma (1); brain glioma (1); breast carcinoma (1); Cognitive impairment (1); conjunctivitis (1); COVID-19 (1); dry eye (1); glioblastoma (1); hepatitis C (1); infection (1); keloid (1); lupus erythematosus (1); Lymph Nodes (1); lymphoma (1); nasal obstruction (1); non-alcoholic fatty liver disease (1); prostate carcinoma (1); sialadenitis (1); small cell lung carcinoma (1).